IRS1 (insulin receptor substrate 1)
Diseases named in the same sentence as IRS1 in open-access papers (continued):
Sharing a sentence is not in itself a finding about the gene and the disease.
hyperuricemia (12 papers, 2016 to 2024). An abnormally high level of uric acid. "Second, hyperuricemia can increase reactive oxygen species production and inhibit insulin-induced glucose uptake by increasing the phosphorylation of insulin receptor substrate 1 and inhibiting the phosphorylation of Akt." (PMID 34335617, 2021). "Antioxidant N-acetyl-L-cysteine could inhibit ROS production and block hyperuricemia-induced IRS1 activation and Akt inhibition." (PMID 35755073, 2022). "The hyperuricemia‐induced oxidative stress could inhibit insulin signaling through the phosphorylation of Akt and insulin receptor substrate‐1 (IRS‐1), and/or lowering phospho‐Akt content in the adipose tissue without changes in total Akt." (PMID 31782919, 2019). "Hyperuricemia increased the phospho-IRS1 (Ser307) level in mouse cardiac tissues." (PMID 26836389, 2016). "We also describe the capacity of these compounds to modulate insulin receptor and insulin receptor substrate 1 via PTP inhibition, to promote glucosuria via SGLT2 inhibition and to suppress hyperuricemia." (PMID 35008779, 2021). "In particular, hyperuricemia inhibited a protein kinase B (AKT) response to insulin by decreasing its phosphorylation and conversely increasing the phosphorylation of the insulin receptor substrate-1 (IRS1) in liver, muscle and fat tissue, thus fostering the onset of IR." (PMID 27077854, 2016).
coronary artery disease (11 papers, 2014 to 2025). "One example is that a body fat-decreasing allele near IRS1 was also associated with adverse lipid profiles, and increased risks for coronary artery disease and type-2 diabetes." (PMID 32737415, 2020). "In detail, carriage of the G allele of rs13431554 in the insulin receptor substrate-1 gene was associated with a hyperreactive platelet phenotype in diabetics with coronary artery disease." (PMID 30268122, 2018). "A two‐stage genome‐wide association meta‐analysis identified a locus near insulin receptor substrate 1 (IRS1) gene that is associated with reduced body fat percentage but also with an impaired metabolic profile, including increased IR and risk of coronary artery disease." (PMID 36071605, 2022). "Whether there is other SNP in IRS-1 related to HPR in coronary artery disease (CAD) and T2DM patients remains to be elucidated." (PMID 27005817, 2016).
melanoma (11 papers, 2015 to 2024). A malignant, usually aggressive tumor composed of atypical, neoplastic melanocytes. "In fact, NT157 has been shown to increase serine phosphorylations that mark IRS1 for proteosomal degradation in the melanoma cell line A375." (PMID 32667922, 2020). "The most promising candidates, which are expected to reduce cell growth and increase apoptosis in melanoma, involve targeting the combination of IRS1 and EGFR." (PMID 32667922, 2020). "Phosphorylation of IRS1 re-enforces the importance of IGF signaling in drug resistant melanoma as a valid target for co-therapy." (PMID 26029660, 2015). "IRS-1 remained significantly higher in NRAS mutant vs BRAF mutant melanomas at the protein level." (PMID 33082316, 2020). "Expression studies, besides confirming IRS‐1 down‐regulation in miR‐126‐transduced A375M melanoma compared with TripZ control cells, showed the strong induction of IRS‐1 in PIK‐75 + vemurafenib cotreated A375M cells, a result suggestive of the association of its activation with drug resistance." (PMID 31115969, 2019). "Importantly, our study provided evidence for signaling events in several proteins (IGFR2, IRS1, PKC, and GEFs) associated with established pathways of drug resistance in melanoma and other cancers." (PMID 26029660, 2015). "Since, at present, anti‐cancer drugs targeting IRS‐1 protein are not available, our data may represent preclinical proof of concept for miR‐126‐based direct targeting of IRS‐1, increasing the possible role of this miR in cancer therapy, including drug‐resistant melanoma." (PMID 31115969, 2019). "We noted higher expression of IGF-receptors, IGF-IR and IGF-IIR and IGF receptor substrates, IRS1 and IRS2 in the epithelial-like melanoma cell lines examined." (PMID 25940796, 2015). "In melanoma, an analysis of 54 melanoma cell lines by whole genome microarray expression profiling revealed upregulation of IGF-receptors (IGF-IR and IGF-IIR) and IGF-R substrates (IRS1 and IRS2)." (PMID 38395880, 2024). "Finally, the top SNP of the SSC15 region was located only 162 kb away from IRS-1 (insulin receptor substrate 1), coding for the protein transmitting signals from the IGF-1 receptor to PI3K/AKT and ERK/MAPK pathways, known to be involved in melanoma." (PMID 29963229, 2018). "In addition, recent studies demonstrated that acquired resistance to the B-RAFV600E/K inhibitor in melanoma is mediated by increased levels of IGF-1R and IRS-1, and this resistance can be effectively reversed by treatment with NT157." (PMID 26029165, 2015).
osteosarcoma (11 papers, 2013 to 2023). A usually aggressive malignant bone-forming mesenchymal neoplasm, predominantly affecting adolescents and young adults. "This showed inhibition of phosphorylation of IRS-1 and of strong inhibition of proliferation in 3/4 osteosarcoma cell lines." (PMID 23688189, 2013). "Treatment of osteosarcoma cells with OSI-906 at physiological levels leads to decreased phosphorylation of IRS-1 at Y612." (PMID 23688189, 2013). "Most importantly, phosphorylated IRS-1, which is a measure for pathway activity, was detected in all four osteosarcoma cell lines, indicating that IGF1R signaling is active in osteosarcoma, and is possibly regulated upstream of IGF1R." (PMID 23688189, 2013). "Phosphorylation of IRS-1, a direct downstream target of IGF1R signaling, was inhibited in the responsive osteosarcoma cell lines." (PMID 23688189, 2013). "Treatment with OSI-906 resulted in inhibition of phosphorylation of IRS-1 Y612, a direct downstream target of IGF1R, and in strong inhibition of proliferation in 3 of 4 osteosarcoma cell lines." (PMID 23688189, 2013). "Moreover, mRNA expression of IGF1 and IGF2 in osteosarcoma cells were increased, while the insulin receptor (INSR) and insulin receptor substrate 1 (IRS1) genes were both downregulated." (PMID 37755271, 2023). "In osteosarcoma, SMARCAL1, IRS1, SUB1, HMGA2, and FANCM were identified as Supertargets." (PMID 37297004, 2023). "An inhibition of intrinsic IRS-1 phosphorylation at Y612 was detected after treatment with OSI-906 in all cell lines, indicating that this inhibitor could affect signaling downstream IGF1R in osteosarcoma cells." (PMID 23688189, 2013).
polycystic ovary syndrome (11 papers, 2006 to 2025). A disorder that manifests as multiple cysts on the ovaries. "In polycystic ovaries, IRS1 expression was decreased in the granulosa cells of the follicle and increased in the theca cells of the follicle compared with that in normally ovulating ovaries." (PMID 40747301, 2025). "In women with polycystic ovary syndrome (PCOS), elevated chemerin expression in granulosa-lutein cells is associated with reduced insulin sensitivity due to impaired IRS1/2 and Akt phosphorylation." (PMID 41457200, 2025). "This, in turn, activates the TLR4 receptor, triggering pathways such as NF-κB and MAPK, which promote insulin resistance through mechanisms like IRS-1 serine phosphorylation, as well as hyperandrogenemia and ovarian dysfunction." (PMID 40842497, 2025). "In human ovarian cells (Polycystic ovarian syndrome- PCOS) aberrant autophagy induction upon release of the high mobility group box 1(HMGB1) plays a role in achieving insulin resistance by downregulating IRS-1, AKT, and GLUT4 translocation." (PMID 38347575, 2024). "Furthermore, follicles retrieved from polycystic ovaries show abnormal patterns of expression of IRS-1 and -2 compared to healthy ones." (PMID 38540265, 2024). "IRS1 and GLUT4 mRNA levels were lower in the proliferating endometrium of patients with polycystic ovaries compared with BMI-matched controls." (PMID 36589857, 2022).
Brain atrophy (10 papers, 2017 to 2025). Partial or complete wasting (loss) of brain tissue that was once present. "Recent studies have revealed that AD brain atrophy is associated with IRS-1 expression, showing a positive relationship with IRS-1 Tyr phosphorylation and a negative relationship with IRS-1 Ser phosphorylation." (PMID 41280311, 2025). "In diabetic patients, the level of the phosphorylated form of insulin receptor substrate 1 in neural-derived exosomes also showed a higher accuracy in predicting the development of AD, which is associated with regional brain atrophy." (PMID 30965555, 2019). "We recently published a study showing that levels of pSer312-IRS1 in extracellular vesicles (EVs) enriched for neuronal origin are associated with brain atrophy in a regional pattern that corresponds to IRS1 expression." (PMID 28515688, 2017). "Moreover, the pS312-IRS-1/p-tyrosine-IRS-1 ratio in neuronal EVs has also been associated with the degree of brain atrophy in AD patients due to the volume of brain regions showing the presence of pS312-IRS-1, as assessed by magnetic resonance image." (PMID 33362690, 2020). "However, plasma exosomal biomarkers of brain IR, such as higher pSer312-insulin receptor substrate 1(IRS-1) (ineffective insulin signaling) and lower p-panTyr-IRS-1 (effective insulin signaling), are linked with brain atrophy in AD and reflect regional IRS-1 expression." (PMID 40379890, 2025). "Therefore, the IRS-1 phosphorylation pattern seen in these EVs may reflect its phosphorylation status in specific brain regions that suffer brain atrophy in early AD in association with higher burden of brain IR." (PMID 28515688, 2017). "A low tyrosine phosphorylated insulin receptor substrate 1 (IRS1) to serine phosphorylated IRS1 ratio is a characteristic of insulin dysregulation and is related to greater brain atrophy in AD patients." (PMID 32547364, 2020). "show that plasma exosomes from AD patients exhibit higher pSer-IRS-1 levels and lower pTyr-IRS-1 compared to control subjects, suggesting that these biomarkers might be associated with the brain atrophy observed in AD." (PMID 29743868, 2018). "Insulin dysregulation can be characterized by low ratios of tyrosine phosphorylated insulin receptor substrate 1 (IRS1) to serine phosphorylated IRS1 and has been correlated with greater brain atrophy in humans with AD." (PMID 31182115, 2019).
lung adenocarcinoma (10 papers, 2019 to 2025). A carcinoma that arises from the lung and is characterized by the presence of malignant glandular epithelial cells. "Houghton AM and colleagues conducted experiments utilizing a mouse lung adenocarcinoma LSL-K-ras model to explore the impact of NE-mediated degradation of IRS-1 on lung cancer growth." (PMID 38750338, 2024). "NE can enter the endosomal compartment within tumor cells, degrade insulin receptor substrate-1 (IRS-1), and directly induce tumor cell proliferation in human and mouse lung adenocarcinoma." (PMID 38750338, 2024). "Neutrophil elastase directly induces tumor cell proliferation in both human and mouse lung adenocarcinomas by providing access to an endosomal compartment within tumor cells, where it cleaves insulin receptor substrate-1 (IRS-1)." (PMID 39596977, 2024). "Neutrophil elastase directly induced tumor cell proliferation in human and mouse lung adenocarcinomas by entering an endosomal compartment and degraded insulin receptor substrate-1 (IRS-1)." (PMID 36942262, 2023). "The aim of this study is to investigate the effect of miR-144-3p on the invasion and metastasis of lung adenocarcinoma by targeting recombinant insulin receptor substrate 1 (IRS1)." (PMID 34034455, 2021). "Survival analysis showed that patients with lung adenocarcinoma with high IRS1 expression had a poor prognosis (P < 0.05)." (PMID 34034455, 2021). "SH2B1 enhanced the EMT process in lung adenocarcinoma through the IRS1/β‐catenin axis." (PMID 31984680, 2022). "The expression of IRS1 was up-regulated in lung adenocarcinoma tissues." (PMID 34034455, 2021). "Transwell experiment proved that miR-144-3p could inhibit invasion and metastasis of lung adenocarcinoma cells by targeting IRS1 (P < 0.05)." (PMID 34034455, 2021). "Interestingly, the authors identified in human lung adenocarcinoma an inverse correlation between NE and IRS-1." (PMID 31616408, 2019). "There, it degrades the insulin receptor substrate 1 (IRS-1) which increases the interaction between PI3K and PDGFR, thereby promoting their proliferation in a LSL-K-ras model of murine lung adenocarcinoma and in human lung adenocarcinoma cell lines." (PMID 31616408, 2019). "Besides, our previous study reported that SH2B1 could interact with insulin receptor substrate 1 (IRS1) to increase its expression, which facilitated epithelial–mesenchymal transition of lung adenocarcinoma cells." (PMID 41410190, 2025).
overnutrition (10 papers, 2015 to 2024). An imbalanced nutritional status resulting from excessive intake of nutrients. "Although acute lipid infusion results in transient IR, as evidenced by an increase in inhibitory serine phosphorylation of insulin receptor substrate-1 (IRS1), chronic overnutrition can induce long-term transcriptional and physiological changes in SM." (PMID 28545403, 2017). "Recently, a programmed increase in miR-126, was shown to repress translation of its Irs1 target in WAT from mice exposed to maternal overnutrition in early life." (PMID 26965244, 2016). "Prenatal overnutrition impacts were most abundant in the duodenum where HIGH had increased villus amplification factor and lowered villi thickness with increased IRS‐1 and reduced GH‐R expressions." (PMID 32597039, 2020). "In overnutrition status, the excess intra-cellular free fatty acids will lead to the activation of PKC and NFκB, then induce serine 307 phosphorylation for IRS-1, which inhibits the insulin signal pathway and eventually results in IR in the skeleton muscle and hepatocytes." (PMID 33019649, 2020). "One of the well described negative feedback loops takes place in response to overnutrition‐induced constitutive mTORC1 activation which leads to inhibitory phosphorylations on IRS‐1 by S6K1. mTORC1 itself also phosphorylates IRS1 to promote its proteasome‐dependent degradation." (PMID 34319011, 2021).
breast tumors (9 papers, 2006 to 2024). "As the majority of these ER+ tumours were found to express low and/or negative erbB2 levels, these findings directly support our cell line work and suggest that an association between erbB3 and IRS-1 may well occur within ER+ breast tumours." (PMID 21939528, 2011). "IRS1 expression is highest in well-differentiated ER + luminal breast tumors, and expression decreases as tumors become more poorly differentiated." (PMID 39305958, 2024). "They observed that lipin-1 expression was correlated with the level of insulin-receptor substrate 1 (IRS1) in breast tumor samples and that lipin-1 co-localizes and directly interacts with IRS1." (PMID 33922580, 2021). "The Late IRS-1 gene signature reported the highest significance in terms of functional pathway analysis and gene set enrichment in molecular breast tumor subtypes." (PMID 26991655, 2016). "Indeed, IRS-1 has been reported to be overexpressed and constitutively phosphorylated in breast tumours, and high expression of this adaptor protein has been associated with lymph node metastases and poor patient prognosis." (PMID 21939528, 2011). "Importantly, a significant positive correlation between IRS-1 Y612 phosphorylation and total erbB3 expression was observed in these ER+ primary breast tumours." (PMID 21939528, 2011). "In addition, high levels of IRS-1 expression have been shown to correlate with early disease recurrence in oestrogen receptor-positive primary breast tumours." (PMID 17043687, 2006). "This novel interaction may have clinical relevance, as immunohistochemical analysis of a small ER+ breast tumour series revealed significant positive correlations between phosphorylated IRS-1 Y612 expression and total erbB3, phosphorylated Akt and Ki-67 expression." (PMID 21939528, 2011). "Both IRS1 and IRS2 are expressed in breast tumors, but their expression patterns and functions differ in a subtype-dependent manner." (PMID 39305958, 2024). "Multiple IRS-1 and IRS-2 clones [IRS-1 (#10 and #20) and IRS-2 (#1 and #6)] were included in these and all subsequent analyses as a means to circumvent both clonal and temporal bias and more accurately depict the role of IRS adaptor proteins in breast tumor biology." (PMID 26991655, 2016). "IRS-2 is highly expressed in invasive breast tumors, whereas IRS-1 is predominantly expressed in localized tumors, and rescue of IRS-2, but not IRS-1, expression in IRS1/2 double null breast tumor cells restores invasive potential." (PMID 36556357, 2022).
gestational diabetes mellitus (9 papers, 2014 to 2026). "we performed this meta- analysis to investigate the impact of insulin receptor substrate 1 (IRS1) gene rs1801278 on susceptibility to gestational diabetes mellitus (GDM)." (PMID 38448958, 2024). "Potential involvemehasof hsa-miR-875-5p to regulate TNF, LEP and IRS1 genes in gestational diabetes mellitus was demonstrated in a recent study." (PMID 33670024, 2021). "SMTNL1 also acts as an insulin-sensitizing agent by increasing the gene expression of PP2A and DUPS9 protein phosphatases, resulting in decreased ERK1/2 activity and, hence, decreasing the phosphorylation of IRS-1 at Ser612 under gestational diabetes conditions." (PMID 38883605, 2024).
liver cancer (9 papers, 2016 to 2026). An epithelial or non-epithelial malignant neoplasm that arises from the liver. "indicates that the expression levels of PYCR1 and IRS1 may serve as potential diagnostic biomarkers for liver cancer." (PMID 41458606, 2025). "Schematic diagram illustrating the mechanism by which PYCR1 knockout/inhibition hinders liver cancer (LC) progression by regulating IRS1 expression through lactylation." (PMID 39422696, 2024). "ZBTB7B bound to the promoters of known ZBTB7B targets genes, e.g., Irs1, as well as genes important in liver cancer, including Jun, Akt1, Ccnd1, and Mki67." (PMID 38225233, 2024). "Recent data obtained in a model of liver cancer induced by diethylnitrosamine, confirm the role of the IR-A/IRS-1 system deregulation in this neoplasia." (PMID 30453495, 2018). "The overexpression of the IR and the associated glycogen accumulation mediated by the IRS-1 and IRS-2 pathways, have been observed in an early phase of hepatocarcinogenesis in a rat model of liver cancer induced by genotoxic N-nitrosomorpholine exposition." (PMID 30453495, 2018). "PYCR1 promotes the growth and metastasis of liver cancer cells by regulating IRS1 expression." (PMID 41458606, 2025). "In summary, the detection of PYCR1, IRS1, Nucleolin lactylation, MADD, HDAC1, and HDAC2 holds potential clinical value in early diagnosis, prognosis assessment, and personalized treatment of liver cancer." (PMID 41458606, 2025). "TAZ has previously been shown to regulate IRS2 expression in liver cancer and to alter insulin sensitivity, but we did not observe effects of TAZ on IRS1/2 expression or insulin sensitivity in mice." (PMID 34622775, 2021).